SPP1 (secreted phosphoprotein 1)
Diseases named in the same sentence as SPP1 in open-access papers (continued):
Sharing a sentence is not in itself a finding about the gene and the disease.
cancer (continued). "In these cancers, the overexpression of SPP1 is associated with poor prognosis." (PMID 40141426, 2025). "Mechanistically, SPP1+ TAMs interact with cancer-associated fibroblasts (CAFs) at the invasive margins via SPP1–integrin/CD44 signaling, driving CAF activation, ECM deposition, and chemokine release, which establishes a stromal barrier that excludes CD8+ T cells and promotes ICB resistance." (PMID 41225975, 2025). "Numerous studies have linked SPP1 to pathological physiological conditions, including cancer." (PMID 39143438, 2024). "Also, our study found that SPP1 was differentially expressed in tumors and normal tissues, and in these tumors was positively correlated with the infiltration of immune cells, whereas high expression of SPP1 in some cancers was associated with poor prognosis." (PMID 38648200, 2024). "In addition, upregulation of the SPP1 signaling pathway was also observed in mM2-like TAMs, with the poor prognosis-associated characteristics of SPP1 in most cancers including PAAD, as previously reported." (PMID 39507421, 2024). "While SPP1 has been linked to cancer cell growth and immune processes, its specific impact on the TNBC prognosis remains unclear, and the interactions between SPP1 and immune regulation in TNBC have yet to be fully understood." (PMID 39727934, 2024). "SPP1 is also significantly associated with adverse survival outcomes in various cancers." (PMID 38956502, 2024). "Moreover, SPP1 is associated with multiple types of pain, such as diabetic NP, cancer pain, and low back pain." (PMID 38415922, 2024). "Previous studies revealed that SPP1+ TAMs showed higher M2 signatures and were associated with increased resistance to anti-PD-L1 therapy because they reduce lymphocyte infiltration across cancers." (PMID 36950551, 2023). "OPN (also known as spp1, Eta-1, and 2ar) is a secreted cytokine-like factor that can affect a range of cell types and is associated with immune response, bone metabolism, and cancer metastasis." (PMID 37079375, 2023). "Interestingly, a recent study of liver tumor also described that the co-enrichment of CCL3+ neutrophils and SPP1+ macrophages was associated with poor prognosis, indicating a similar mechanism across different cancer types." (PMID 36869384, 2023). "Altogether, these data suggested that the intracellular localization (cytoplasmic and nuclear) of SPP1 or one of its splice variants merit further investigation, as it might have a clinical impact for cancer patients." (PMID 38067407, 2023). "Additionally, the significantly positive associations of enrichment scores of CAFEndMT and SPP1+ TAMs were also validated in 25 of 28 cancer types in the TCGA dataset, further supporting the possible proximity of SPP1+ TAMs and CAFEndMT." (PMID 36333338, 2022). "SPP1 expression was significantly associated with the degree of infiltration in macrophages (M0, M1, and M2), resting mast cells, B cells, and neutrophils in at least six types of cancer according to CIBERSORT analysis." (PMID 35067176, 2022). "SPP1, also known as osteopontin, is involved in a variety of biological processes, including bone remodeling, innate immunity, acute and chronic inflammation, and cancer, and is closely associated with cell apoptosis." (PMID 35629036, 2022). "Thus, future research is needed to elucidate the roles of SPP1 and explore the underlying molecular mechanism of SPP1 in cancer progression." (PMID 34676217, 2021). "This evidence supports the use of SPP1 as a broad-spectrum diagnostic and therapeutic in cancer." (PMID 33996808, 2021). "Expression of SPP1 is associated with poor prognosis in a number of cancers." (PMID 33187209, 2020). "Based on these effects, we proffered that there may be a possible association between the expression of OCT4 and SPP1 variants in cancer cells." (PMID 32503462, 2020). "However, the specific role of SPP1 in prognosis, gene mutations, and changes in gene and miRNA expression in human cancers is unclear." (PMID 33324676, 2020).
cancer (continued). "SPP1, on the other hand, encodes a multifunctional secreted glycoprotein that is frequently expressed by tissue macrophages, and its engagement with integrin underlies the non-classical macrophage activation, angiogenesis, and migration of cancer cells." (PMID 29483918, 2018). "Moreover, we have also shown that CBX7 counteracts the HMGA-induced activation of the SPP1 gene, encoding the chemokine osteopontin, that is highly overexpressed in several human carcinomas and has a key function in malignant transformation." (PMID 28259135, 2017). "On the other hand, taking into account the molecules involved in cell to cell signaling events, the most DEG was osteopontin (SPP1), which has been found disregulated in several subtypes of cancer which in turn is linked to PLAU and PLAUR, also highly overexpressed." (PMID 25887408, 2015). "Finally, Spp1 (osteopontin) is a well-known vitamin D-regulated cytokine that is associated with ossification, inflammation, chemo-attraction, cancer and hypoxia-induced cell death." (PMID 23741446, 2013). "Beyond immunosuppression, SPP1+ macrophages are deeply implicated in fibrosis, as evidenced by both their transcriptional profile and their interactions with stromal cells, whether cancer‐associated fibroblasts or fibroblast progenitor cells." (PMID 40395129, 2025). "SPP1 (secreted phosphoprotein-1), a multifunctional protein implicated in various physiological and pathological processes, is highly expressed in numerous cancer types, with its expression levels positively correlated with the infiltration of dendritic cells, neutrophils, and macrophages." (PMID 40725440, 2025). "In addition to the M1 versus M2 phenotyping, an alternative classification method using the relative expression levels of CXCL9 and SPP1 has been introduced to assess macrophage polarity, showing that the CXCL9:SPP1 ratio is associated with prognosis in cancer patients." (PMID 39601163, 2024). "Besides, by promoting macrophage secreted phosphoprotein 1 (SPP1) expression and facilitating cancer-associated fibroblast and endothelial cell recruitment and activation through TANs, IFIT1 promotes a mesenchymal phenotype, which is associated with a poor prognosis." (PMID 38898490, 2024). "The observation that alternative splice variants of SPP1 may be produced selectively in cancer and that distinct types of cancer may express different combinations of spice variants has opened up the field for a more refined evaluation of the potential for utilizing SPP1 forms in cancer detection." (PMID 39727934, 2024). "The differential expression of SPP1 in the tissue and plasma samples and its association with poor prognosis in cancer patients with an advanced disease stage indicated that SPP1 may serve as a valuable prognostic biomarker in different solid tumors and a potential target for cancer therapy." (PMID 38067407, 2023). "Mechanistically, sustained tumor cell-derived IFN induced osteopontin (SPP1) expression in TAMs via STAT signaling, creating immunosuppressive niches enriched in Tregs and myofibroblastic cancer-associated fibroblasts with intensified cell-cell interactions." (PMID 41734034, 2026). "Drug-sensitivity predictions showed high-SPP1 tumors were more sensitive to several anti-cancer drugs (e.g., sorafenib), while resistance to others was suggested." (PMID 42018581, 2026). "Through this study, we have identified characteristics of TME in patients experiencing recurrence after CCRT treatment, showing heightened interaction between SPP1‐positive macrophages and cancer cells via CD44 or ITGB1." (PMID 41466485, 2026). "SPP1+ TAMs transcend the traditional M1/M2 paradigm and represent a group of cells that are widely found in various cancer types." (PMID 41751193, 2026). "The flow cytometry analysis showed that knockdown of ITGA4 or ITGB1 can inhibit the effect of recombinant SPP1 protein or cancer cells on the function of CD8+T cells (Additional file3N)." (PMID 40665335, 2025).
cancer (continued). "The analysis revealed that high levels of SPP1 expression were widespread across the 22 cancer types studied." (PMID 40196737, 2025). "An interaction network consisting of seven ligand‐receptor pairs representative of the SPP1 signalling pathway was identified to induce the communications among cancer cells, T cells and VasECs in BM of NSCLC." (PMID 39231761, 2025). "A study integrating three datasets revealed enhanced expression of CCL20 in SPP1+ macrophages, which is believed to facilitate cancer cell migration and proliferation, while remodeling the TME to accelerate cancer progression." (PMID 40191203, 2025). "Previous studies have established the potentially opposing roles of CXCL9 and SPP1 in cancer biology." (PMID 40936719, 2025). "Their research demonstrated that SPP1 supports cancer cell survival during androgen deprivation therapy through the PI3K/AKT and ERK1/2 pathways, as seen in patient-derived organoids and CRPC cell lines." (PMID 41391064, 2025). "In our results, the overexpression of miR-210-3p in HCC cells induced SPP1+ macrophages, promoting cancer cell proliferation." (PMID 40416872, 2025). "In conclusion, SPP1+ macrophages represent a fascinating convergence of biology across aging, inflammation, and cancer." (PMID 40047497, 2025). "Another study found that SPP1 helps cancer cells evade the immune system via the WDR5-H3K4me3 pathway." (PMID 41391064, 2025). "SPP1 not only contributes to primary lung malignancy but also promotes lung metastasis of other cancers, such as melanoma." (PMID 40559389, 2025). "The analysis results showed that Macrophages_FABP4 exhibited significant depletion in cancer tissues, while Macrophages_SLENOP, Macrophages_SPP1, Macrophages-STMN1, and Macrophages_CXCL10 showed significant enrichment." (PMID 40916017, 2025). "This review aims to provide a comprehensive analysis of SPP1’s role in the development and progression of various cancers, highlighting its potential as a therapeutic target and biomarker for cancer management." (PMID 41391064, 2025). "Our findings suggest that MDSCs or cancer cells in 4T1 tumors express Spp1, Ltf, Calr, and Prdx2, potentially influencing elevated plasma concentrations." (PMID 39939411, 2025). "We showcased the example of SPP1, which has been linked to EMT in various cancers, including NSCLC, but to our knowledge, a limited number of studies exist on SPP1 and EndMT in cancer and should thus be further studied." (PMID 40028673, 2025). "Spp1 gene expression was the highest in 4T1 cancer cells at the late time point, whereas Ltf gene expression was the highest in MDSCs of 4T1‐bearing mice at the late time point." (PMID 39939411, 2025). "SPP1 is overexpressed in various types of cancer; however, research on its relationship with CC is limited." (PMID 40809844, 2025). "In triple-negative BC (TNBC), SPP1+ macrophage and cancer cell interactions driven by hypoxia signaling correlate with poor prognosis." (PMID 41425545, 2025). "Previous study has shown that the cell model expressing high SPP1 level exhibits cancer cell proliferation, migration, invasion and drug resistance to radiotherapy and chemotherapy." (PMID 40495644, 2025). "SPP1 contributes to tumorigenesis and cancer progression through multiple mechanisms, including immune modulation, promotion of cell survival, proliferation, and metastasis." (PMID 40559389, 2025). "Future studies should focus on large-scale clinical trials and more detailed exploration of cellular mechanisms to better understand and harness SPP1’s potential in cancer treatment." (PMID 41391064, 2025). "We further compared the differential Spp1-related interaction intensity between cancer cells (i.e., MC38) and all TME cell types among four treatment groups, identifying the greatest decrease in the PW group, particularly in TAMs and especially Spp1+ TAMs." (PMID 40312419, 2025).
cancer (continued). "The interplay between SPP1-expressing TAMs and cancer cells thus establishes a protumor niche that drives chemoresistance and poor prognosis." (PMID 41391064, 2025). "SPP1 plays a significant role in promoting cancer cell growth and resistance to chemoradiotherapy by inducing epithelial-mesenchymal transition, autophagy, aberrant glucose metabolism, epigenetic changes, and reducing drug uptake." (PMID 41282023, 2025). "Previous studies have indicated that SPP1 is overexpressed in various cancers and can serve as a predictor of poor outcomes, including in ovarian cancer, glioblastoma, hepatocellular carcinoma, and gastric cancer." (PMID 40936719, 2025). "Secreted phosphoprotein 1 (SPP1+) macrophages are a recurrent and functionally critical immune cell subset across multiple cancer types." (PMID 41425545, 2025). "SPP1+ macrophages have been widely described in cancer, aging, and chronic inflammatory diseases, exhibiting conserved functional features including fibrosis promotion, extracellular matrix remodeling, and immune modulation." (PMID 40589761, 2025). "The same NRF2 activation gradient separates pro-inflammatory CXCL9+ and anti-inflammatory SPP1+TAMs across diverse human cancers." (PMID 41176316, 2025). "Spp1, Calr, and Prdx2 were highly expressed in 4T1 cancer cells, whereas Ltf was highly expressed in MDSC within 4T1 tumors." (PMID 39939411, 2025). "mIF results also observed a more prevalent staining pattern of SPP1 in T cells and cancer cells from BM." (PMID 39231761, 2025). "Elevated levels of serum or tissue SPP1 are consistently observed in various cancers, including lung, breast, prostate, and colorectal cancers." (PMID 40559389, 2025). "Recently, SPP1 has been shown to be expressed and secreted by TAMs in various cancers, promoting macrophage polarization, migration, sustained activation, and affecting the cytokine profile of macrophages." (PMID 40230843, 2025). "In conclusion, the results of our analyses confirmed the multifaceted role of SPP1 in several aspects of cancer progression, thus establishing it as one of the most potent oncogenes." (PMID 39857756, 2025). "In a study that integrated three datasets, CCL18 was enhanced in SPP1+ macrophages, which accelerated cancer progression by promoting angiogenesis." (PMID 40191203, 2025). "Cross-cancer analyses demonstrate that SPP1-mediated collagen deposition, stromal fibrosis, and integrin-dependent ECM receptor signaling collectively fuel metastatic dissemination and therapy resistance." (PMID 41293726, 2025). "In this type of cancer, samples showed considerable changes in SPP1 expression with higher disease stage, as represented by Fuhrman grades, with the number of gene signatures increasing as well." (PMID 39857756, 2025). "In this study, we were the first to investigate the causal relationship between SPP1+ TAM-related genes and cancer using MR." (PMID 40376263, 2025). "PDAC cancer cells (cluster 2) expressed receptors for SPP1, MDK, and TWEAK (TNFSF12), with TWEAK showing the strongest interaction (blue frame)." (PMID 41228323, 2025). "In non-small cell lung cancer, SPP1 is higher in the serum of patients with advanced stages (IV) cancer than in patients with stages I–III." (PMID 40559389, 2025). "The mutually exclusive expression of these markers defines TAM polarity, with SPP1-enriched TAMs promoting immune evasion and stromal interactions that drive aggressive disease across multiple cancer types." (PMID 41391064, 2025). "The Anushka team has shown through their studies that the targeting and removal of important elements such as CD73, CSF1, or SPP1 secreted by quiescent metastatic cancer cells can significantly disrupt the establishment of the immunosuppressive TME." (PMID 40303328, 2025). "In this review, we explore the biology of SPP1+ macrophages, both in cancer and non‐cancerous conditions, to provide a comprehensive synthesis of their roles in disease." (PMID 40395129, 2025).
cancer (continued). "Given their prevalence and pivotal role, SPP1+ macrophages have become a major focus in cancer immunology and a promising target for therapeutic development." (PMID 41425545, 2025). "By utilising the CancerSEA database, we assessed the potential function of SPP1/HMOX1 among pan‐cancer." (PMID 40495644, 2025). "Targeting the CD44/SPP1 and integrin/SPP1 axes represents a promising strategy for cancer therapy, as these interactions play critical roles in the TME." (PMID 41391064, 2025). "Through interactions with multiple receptors, SPP1 activates key cancer-related signaling pathways that promote cell survival, proliferation, migration, and invasion." (PMID 41391064, 2025). "The link between SPP1+ macrophages and cancer is well established, with TAMs representing the archetype of this subpopulation." (PMID 40047497, 2025). "Specifically, genes such as STC1 (PAI 6: Vertebrata), VCAN (PAI 7: Euteleostomi), and SPP1 (PAI 9: Eutheria)—key regulators of such hallmarks of cancer as angiogenesis and metastasis in tumors." (PMID 40507851, 2025). "The SPP1-CD44 interaction was identified as the most influential in cancer progression, with SPP1 highly expressed in TAMs and CD44 overexpressed in neoplastic-stemness cells." (PMID 40076844, 2025). "In the intrinsic view, KLK6-positive cells showed increased proximity to cancer-associated fibroblasts (myCAF, iCAF), plasma cells, SELENOP+ macrophages, SPP1+ macrophages, MK167+ macrophages, and endothelial cells." (PMID 41383634, 2025). "These cells, marked by high expression of the pan‐macrophage marker CD68 and SPP1, have been strongly correlated with poor prognosis and cancer progression." (PMID 40395129, 2025). "These conserved functions, alongside their context‐specific behaviours, highlight SPP1+ TAMs as a distinct macrophage lineage with broad implications for cancer progression and therapeutic resistance." (PMID 40395129, 2025). "In conclusion, our comprehensive characterization of the immune microenvironment in multiple sites of OC reveals a subset of PLIN2hi macrophages that are enriched in ascites and promote ascitic development and cancer metastasis through HIF1α/SPP1 signaling." (PMID 39921309, 2025). "The flow cytometry analysis showed that knockdown of ITGA4 or ITGB1 can inhibit the effect of recombinant SPP1 protein or cancer cells on M2 TAM polarization (Additional file4N)." (PMID 40665335, 2025). "The identification of SPP1+ TAMs in cancers as a prognostic biomarker has important clinical implications." (PMID 41225975, 2025). "To further investigate the phagocytic ability of SPP1 + macrophages in various cancer types in addition to ESCC, we extracted and integrated myeloid cells from scRNA-seq data of ESCC, HCC, COAD, NSCLC, STAD, and PDAC." (PMID 39696410, 2024). "The persistent estrogenic response, activation of ERα and ERRα, and overexpression of SPP1 following GCRsim exposure indicate a complex interplay between hormonal signaling, inflammation, and cancer development." (PMID 39682141, 2024). "Nevertheless, comprehensive scRNA-Seq analysis from different human cancer types was able to classify the possible moTAM populations into two groups: SPP1+ macrophages and C1QC+ macrophages." (PMID 39430099, 2024). "SPP1 facilitated cancer cell chemoresistance by activating the CD44 receptor, and anti-SPP1 and anti-CD44 antibodies improved cancer cell sensitivity to cisplatin in a mouse model." (PMID 38521868, 2024). "In prostate, cervical, breast, liver, and other cancers, SPP1 is substantially expressed and correlated with clinical stage and prognosis." (PMID 38329443, 2024). "Previous research has demonstrated that SPP1 serves an important function in cellular signaling, facilitation of angiogenesis, and evasion of immune responses across various cancer types." (PMID 38191424, 2024). "In cancer models, SPP1 can induce COX-2 expression, promote matrix metallopeptidase expression, and promote angiogenesis." (PMID 39911634, 2024).